RASSF7 (Ras association domain family member 7)
Description:
Negatively regulates stress-induced JNK activation and apoptosis by promoting MAP2K7 phosphorylation and inhibiting its ability to activate JNK. Following prolonged stress, anti-apoptotic effect stops because of degradation of RASSF7 protein via the ubiquitin-proteasome pathway. Required for the activation of AURKB and chromosomal congression during mitosis where it stimulates microtubule polymerization.
Synonyms: C11orf13; HRC1; HRAS1; FAP88; CFAP88
Tractability: PROTAC: UniProt records ubiquitination sites on it; ubiquitination databases record sites on it.
Gene: Protein-coding gene on chromosome 11 (560,207 to 564,067, forward strand). Ensembl gene ENSG00000099849.
Subcellular location: Cytoplasm, cytoskeleton, microtubule organizing center, centrosome
Subcellular location (Human Protein Atlas): Centriolar satellite
Gene Ontology:
Molecular function: protein binding
Biological process: signal transduction
Cellular component: centriolar satellite; centrosome
Genetic constraint (gnomAD): Loss-of-function variants: 47 observed, 31.51 expected, observed/expected ratio (o/e) 1.49, 90% interval 1.18 to 1.86. The synonymous counts are far from expectation, so gnomAD's model fits this gene poorly and the ratio says little. Missense variants: 622 observed, 466.97 expected, observed/expected ratio (o/e) 1.33, 90% interval 1.25 to 1.42. Synonymous variants: 298 observed, 200.72 expected, observed/expected ratio (o/e) 1.48, 90% interval 1.35 to 1.63.
Homologues: Orthologues: chimpanzee RASSF7 (99% identical), macaque RASSF7 (94% identical), dog RASSF7 (82% identical), pig RASSF7 (79% identical), mouse Rassf7 (74% identical), guinea pig RASSF7 (72% identical), rat Rassf7 (66% identical), tropical clawed frog rassf7 (42% identical), zebrafish rassf7b (35% identical), zebrafish rassf7a (35% identical), Drosophila melanogaster RASSF8 (22% identical), Caenorhabditis elegans K05B2.2 (19% identical). Paralogues in human: RASSF8 (35% identical), RASSF10 (20% identical), RASSF9 (15% identical).
Diseases named in the same sentence as RASSF7 in open-access papers:
RASSF7 is named in the same sentence as 15 diseases in open-access papers, as found by Europe PMC text mining. Sharing a sentence is not in itself a finding about the gene and the disease. The quoted sentences say what the papers report.
endometrial cancer (2 papers, 2017 to 2021). Primary or metastatic malignant neoplasm involving the endometrium (mucous membrane that lines the endometrial cavity). "RASSF7 is overexpressed in pancreatic and endometrial cancers and ovarian clear cell carcinoma." (PMID 29108261, 2017).
gastric cancer (2 papers, 2021). A primary or metastatic malignant neoplasm involving the stomach. "For example, expression of CDKN1C, RASSF7, GPRC5A, and MPZL2 were all significantly related to KLF5 in gastric cancer tissue." (PMID 33923166, 2021).
lung carcinoma (2 papers, 2017 to 2019). "Among RASSF family members, RASSF7 functions as an oncogene in lung cancer progression by inhibiting the phosphorylation of mammalian Ste20-like kinase 1, large tumor suppressor kinase 1 and yes-associated protein." (PMID 31768130, 2019). "RASSF7 also presented high nuclear expression in lung cancer tissues, a finding that warrants further research." (PMID 29108261, 2017). "This RASSF7 overexpression promoted lung cancer cell proliferation, migration, and invasion." (PMID 29108261, 2017). "To investigate the function of RASSF7 in NSCLC, we evaluated the expression level of RASSF7 protein in a panel of lung cancer cell lines using western blot." (PMID 29108261, 2017).
neuroblastoma (2 papers, 2012 to 2015). Neuroblastoma (NB) is the most common solid, extracranial childhood tumor. "RASSF5 and RASSF6 were to various degrees methylated in a large portion of neuroblastoma tumors and RASSF7 was heavily methylated in most tumors." (PMID 22695170, 2012). "The genes RASSF5, RASSF6 and RASSF7 stand out as the most promising candidate genes for further investigations in neuroblastoma." (PMID 22695170, 2012). "In the current study, we found that several of the RASSF family genes (RASSF2, RASSF4, RASSF5, RASSF6, RASSF7, and RASSF10) to various degrees were methylated in neuroblastoma cell lines and primary tumors." (PMID 22695170, 2012). "However, in neuroblastoma, RASSF6 and RASSF7 showed a promoter methylation and RASSF6 promoter methylation was correlated with an unfavorable outcome." (PMID 25750636, 2015).
breast carcinoma (1 paper, 2017). "Other dysregulated mRNA that can play important roles in tumor cell behavior as per MammaPrint breast cancer profile were the upregulated DTL and RASSF7 mRNA whose proteins are involved in uncontrolled cell cycle and in microtubule cytoskeleton and spindle formation respectively." (PMID 29203780, 2017).
leukaemia (1 paper, 2009). "As determined by COBRA and bisulphite sequencing, RASSF7 was unmethylated in all leukaemia cell lines analysed (0/5)." (PMID 19570220, 2009).
lymph node metastasis (1 paper, 2017). "Statistical analyses revealed that overall RASSF7 and cytoplasmic RASSF7 expression correlated with high TNM stage (P = 0.001 and P < 0.001, respectively) and lymph node metastasis (P < 0.001 and P < 0.001, respectively)." (PMID 29108261, 2017). "High cytoplasmic RASSF7 expression correlated with high TNM stage, lymph node metastasis, and poor patient prognosis." (PMID 29108261, 2017).
mesothelioma (1 paper, 2021). A usually malignant and aggressive neoplasm of the mesothelium which is often associated with exposure to asbestos. "We found RASSF7 amplification in 39 mesotheliomas, NF2 mutations in 24, LATS2 mutations in 6 and LATS1 in 2, so that non-overlapping lesions in Hippo pathways were present in 52/121 mesotheliomas (43%) and a further 9 mesothelioma had more than one lesion (total 50%)." (PMID 34580349, 2021).
non-small cell lung carcinoma (1 paper, 2017). A group of at least three distinct histological types of lung cancer, including non-small cell squamous cell carcinoma, adenocarcinoma, and large cell carcinoma. "In this study, we examined the role of N-terminal Ras-association domain family 7 (RASSF7) in human non-small cell lung cancer (NSCLC)." (PMID 29108261, 2017).
cancer (10 papers, 2008 to 2022). A tumor composed of atypical neoplastic, often pleomorphic cells that invade other tissues. "Apart from Cdkn1c, other cancer-related genes, such as RASSF7 and GPRC5A has also been linked with Klf5 in this study." (PMID 33923166, 2021). "Further, it was shown that RASSF7 downregulation leads to a loss of AURKB activation in cancer cells." (PMID 33915740, 2021). "HRASLS and RASSF7, oncogenic transformation-related genes, have been implicated in contributing to at least three of the hallmarks of cancers (evading apoptosis, self-sufficiency in growth signals, and insensitivity to anti-growth signals) described by Hanahan and Weinberg." (PMID 35626050, 2022). "Methylation of RASSF1, RASSF2, RASSF3, RASSF6, RASSF7, and RASSF9, from the RASSF regulator family was strongly associated with expression of several GMDs in a variety of cancer categories." (PMID 33676569, 2021). "RASSF7 presented negative or low cytoplasmic expression in normal lung tissues and high cytoplasmic expression in carcinoma samples, which also showed positive RASSF7 nuclear expression." (PMID 29108261, 2017). "Unlike the majority of the RASSF family members that are silenced in cancer, RASSF7 has been shown to be upregulated in a number of cancers including pancreatic, endometrial, and ovarian." (PMID 22577550, 2012). "The upregulation of RASSF7 in cancers suggests an oncogenic function, the mechanism of which has only just started to be explored." (PMID 22577550, 2012). "This suggests thepossibility that RASSF7 could have a role in promoting cancer celldevelopment.In our study the under-expression of RASSF7 in USC correlated withgood prognosis and the detection of RASSF7 silencing by methylation study could havepotential clinical use for USC prognosis and treatment." (PMID 21079744, 2010). "However, the relationship between RASSF7 expression and clinicopathologic factors in human cancers has not been reported, and the precise role of RASSF7 in tumors is unknown." (PMID 29108261, 2017).
tumor (5 papers, 2017 to 2021). "Defects in Hippo pathways that included RASSF7 amplification and NF2 or LATS1/2 mutations were present in 50% of tumours and were accompanied by micromolar responses to the YAP1 inhibitor Verteporfin." (PMID 34580349, 2021). "Although there are structural differences between classical and N-RASSFs, RASSF8 and RASSF10 also act as a tumor suppressors while RASSF7 regulates cell growth and apoptosis." (PMID 29108261, 2017). "We identified a recurrent novel amplification of RASSF7 in 31% of tumours." (PMID 34580349, 2021). "Our in vivo experiments demonstrated that tumor volume, weight, and the number of lung metastatic lesions were reduced in mice injected with R7-Mut4-transfected cells as compared to those transplanted with cells expressing full-length RASSF7." (PMID 29108261, 2017). "Tumor volume and weight, as well as the number of lung metastatic nodules, were increased in mice transplanted with RASSF7-overexpressing cells relative to the other two groups." (PMID 29108261, 2017). "We also performed immunohistochemistry to assess the correlation between RASSF7 and p-YAP(s127) in 88 NSCLC tumor specimens." (PMID 29108261, 2017). "Interestingly, Rassf7 was shown to inhibit the MKK7/JNK signaling pathway, Zfp382 was shown to inhibit the transcription of various tumor and migration promoting genes, and Tciam was found to inhibit LPS signaling and NF-κB activity." (PMID 30423977, 2018).
RASSF7 also shares sentences with these, for which no sentence is quoted: ovarian clear cell cancer (2 papers); islet cell tumors (1); pancreatic ductal carcinoma (1); skin tumors (1).